KCNE2 (potassium voltage-gated channel subfamily E regulatory subunit 2)
Description:
Ancillary protein that functions as a regulatory subunit of the voltage-gated potassium (Kv) channel complex composed of pore-forming and potassium-conducting alpha subunits and of regulatory beta subunits. KCNE2 beta subunit modulates the gating kinetics and enhances stability of the channel complex. Associates with KCNH2/HERG alpha subunit Kv channel to form the rapidly activating component of the delayed rectifying potassium current (IKr) in heart. May associate with KCNQ2 and/or KCNQ3 alpha subunits to modulate the native M-type current. May associate with HCN1 and HCN2 channel subunits to increase potassium current (By similarity). Forms a heterooligomer complex with KCNQ1/KVLQT1 alpha subunits which leads to currents with an apparently instantaneous activation, a rapid deactivation process and a linear current-voltage relationship and decreases the amplitude of the outward current. KCNQ1-KCNE2 channel associates with Na(+)-coupled myo-inositol symporter in the apical membrane of choroid plexus epithelium and regulates the myo-inositol gradient between blood and cerebrospinal fluid with an impact on neuron excitability (By similarity).
Synonyms: MiRP1; LQT6; ATFB4; LQT5
Tractability: Antibody: UniProt places it where antibodies can reach, with high confidence; its Gene Ontology location is reachable by antibodies, with high confidence; UniProt predicts a signal peptide or a membrane-spanning region.
Gene: Protein-coding gene on chromosome 21 (34,180,729 to 34,371,381, forward strand). Ensembl gene ENSG00000159197.
Subcellular location: Cell membrane; Apical cell membrane
Pathways (Reactome):
Muscle contraction: Phase 2 - plateau phase; Phase 3 - rapid repolarisation
Gene Ontology:
Molecular function: delayed rectifier potassium channel activity; inward rectifier potassium channel activity; potassium channel regulator activity; protein binding; transmembrane transporter binding; voltage-gated potassium channel activity involved in ventricular cardiac muscle cell action potential repolarization; voltage-gated potassium channel activity
Biological process: cardiac muscle cell action potential involved in contraction; cellular response to xenobiotic stimulus; membrane repolarization; membrane repolarization during action potential; membrane repolarization during ventricular cardiac muscle cell action potential; negative regulation of delayed rectifier potassium channel activity; positive regulation of proteasomal protein catabolic process; potassium ion export across plasma membrane; potassium ion import across plasma membrane; potassium ion transmembrane transport; regulation of heart rate by cardiac conduction; regulation of membrane repolarization; regulation of potassium ion transmembrane transport; regulation of ventricular cardiac muscle cell membrane repolarization; ventricular cardiac muscle cell action potential; monoatomic ion transport; potassium ion transport
Cellular component: cell surface; lysosome; plasma membrane; voltage-gated potassium channel complex; apical plasma membrane; membrane
Genetic constraint (gnomAD): Loss-of-function variants: 5 observed, 6.12 expected, observed/expected ratio (o/e) 0.82, 90% interval 0.42 to 1.64. That is too few expected variants to judge how well the gene tolerates losing a copy. Missense variants: 137 observed, 159.82 expected, observed/expected ratio (o/e) 0.86, 90% interval 0.75 to 0.99. Synonymous variants: 57 observed, 59.02 expected, observed/expected ratio (o/e) 0.97, 90% interval 0.78 to 1.2.
Gene-disease validity (ClinGen):
ClinGen rates the evidence that KCNE2 causes each of these diseases.
long QT syndrome (autosomal dominant): Disputed.
Homologues: Orthologues: chimpanzee KCNE2 (98% identical), macaque KCNE2 (94% identical), pig KCNE2 (93% identical), dog KCNE2 (91% identical), rabbit KCNE2 (87% identical), mouse Kcne2 (85% identical), guinea pig KCNE2 (82% identical), rat Kcne2 (82% identical), tropical clawed frog kcne2 (54% identical). Paralogues in human: KCNE1 (24% identical).
Diseases named in the same sentence as KCNE2 in open-access papers:
KCNE2 is named in the same sentence as 57 diseases in open-access papers, as found by Europe PMC text mining. Sharing a sentence is not in itself a finding about the gene and the disease. The quoted sentences say what the papers report.
gastric cancer (12 papers, 2010 to 2024). A primary or metastatic malignant neoplasm involving the stomach. "Multiple histological evidence proves that KCNE2 is expressed at lower levels in gastric cancer than in normal tissues, and its deficiency is likely to be a potential risk factor for gastric cancer." (PMID 37215115, 2023). "KCNE2 encodes a voltage-gated potassium channel ancillary subunit and is highly expressed in gastric parietal cells, and was suggested to suppress the proliferation of gastric cancer." (PMID 29299148, 2017). "KCNE2 is also downregulated in human gastric carcinoma, and its overexpression has been found to result in a reduced proliferation of GC cells." (PMID 35426084, 2022). "This increases the pathophysiological overlap of Testin with KCNE2, because Kcne2 null mice spontaneously develop gastric cancer." (PMID 33464998, 2021). "Overexpression of KCNE2 in the SGC7901 gastric cancer cell line reduces proliferation and significantly reduces xenograft tumour volume compared to parental SGC7901 cells." (PMID 31071485, 2019). "KCNE2 was previously found to be expressed 2-fold lower in human gastric cancer tissue than in neighboring normal gastric cells, and forced upregulation of KCNE2 had anti-proliferative effects on gastric cancer cells in vitro and injected into nude mice." (PMID 20625512, 2010). "Reduced KCNE2 expression was previously suggested to enhance proliferation in the gastric cancer cell line SGC7901 via increased expression of Cyclin D1." (PMID 20625512, 2010). "Previous research has shown that KCNE2 is expressed at lower levels in gastric cancer." (PMID 39272981, 2024). "KCNE2 was previously identified to be downregulated in gastric cancer and the force expression of KCNE2 could inhibit cancer cell proliferation and cell cycle progression." (PMID 31044566, 2019). "KCNE2 downregulation is observed in gastric cancer tissue and gastric cancer cell lines, correlates with gastritis cystica profunda development (preneoplastic condition characterised by large gastric cysts) and is a risk factor in gastric cancer stratification." (PMID 31071485, 2019). "Given that in a previous study reduced KCNE2 expression was found to enhance gastric cancer cell line proliferation, and KCNE2 expression was found to be reduced in human gastric cancer, we examined KCNE2 expression in normal human gastric mucosa, and gastric cancer tissue." (PMID 20625512, 2010). "Together with the finding here that parietal cell KCNE2 expression appears to be reduced in human gastric cancer tissue and the previous report that KCNE2 inhibits gastric cancer cell proliferation, the data suggest KCNE2 disruption is associated with gastric cancer progression." (PMID 20625512, 2010). "In a recent study, KCNE2 expression was found to be expressed at relatively low levels in human gastric tumors and in gastric cancer cell lines; furthermore, forced over-expression of KCNE2 suppressed the growth of human gastric cancer cells in tissue culture, and in nude mice." (PMID 20625512, 2010). "In addition, KCNE2 expression is estrogen dependent and is down regulated in gastric cancer while its over expression suppresses cell proliferation and tumorgenesis in a gastric cancer cell line." (PMID 20927350, 2010). "Finally, analysis of human gastric cancer tissue indicated reduced parietal cell KCNE2 expression." (PMID 20625512, 2010). "Thus, KCNE2 expression in parietal cells was rarely observed in gastric carcinoma." (PMID 20625512, 2010). "In contrast, in human gastric carcinomas, KCNQ1 and KCNE2 expression rarely overlapped, even though KCNQ1 retained its strong co-localization with HKA β." (PMID 20625512, 2010). "Other evidence has suggested a role for KCNE2 in human gastric cancer cell proliferation, independent of its role in gastric acidification." (PMID 20625512, 2010). "However, some genes such as HOXC9, FNDC1, STRA6, KCNE2, PGA3 and KCNJ16 haven’t been reported in gastric cancer and their roles remain unknown." (PMID 25928635, 2015).
gastric cancer (continued). "However, it is not yet known whether KCNE2 downregulation contributes to gastric cancer progression through a failure to acidify the lumen of the stomach or via its role in regulating tumour cell proliferation." (PMID 31071485, 2019).
long QT syndrome (11 papers, 2010 to 2025). "Susceptibility genes can be analyzed, such as KCNQ1, KCNH2, KCNE1, and KCNE2, which are involved in long QT syndrome, the RYR2 gene implicated in catecholaminergic polymorphic ventricular tachycardia type 1, or the SCN5A gene associated with Brugada syndrome." (PMID 40361926, 2025). "Recent research has demonstrated that mutations in KCNE2, namely T8A and Q9E, can lead to long QT syndrome (LQTS)." (PMID 39272981, 2024). "Scientific studies have demonstrated that mutations in the KCNE2 gene or aberrant protein expression can give rise to long QT syndrome (LQTS)." (PMID 39272981, 2024). "Previous studies have found that mutations in KCNH2 or KCNE2 can also cause AF, in addition to long QT syndrome, ventricular arrhythmia, and sudden death." (PMID 37759586, 2023). "Mutations in KCNE2 in human heart causes a long QT-syndrome and ventricular fibrillation by diminishing potassium currents while mouse null mutations in Kcne2 increase the excitability of cortical pyramidal neurons." (PMID 28344592, 2017). "Alterations in KCNE2 associates with human cardiac arrhythmogenesis and long QT syndrome, as well as with down regulation of two major components of murine cardiac action potential repolarization currents and changes in gastric secretion." (PMID 20927350, 2010). "In this context, susceptibility genes can be analyzed, such as KCNQ1, KCNH2, KCNE1, and KCNE2, which are involved in long QT syndrome, the RYR2 gene implicated in catecholaminergic polymorphic ventricular tachycardia type 1, or the SCN5A gene associated with Brugada syndrome." (PMID 40361926, 2025). "Moreover, novel associations between three genes (KCNQ1, KCNH2, and KCNE2) associated with Long QT syndrome and HCM phenotype were proposed." (PMID 28750076, 2017). "Mutations in KCNE2 have been associated with long-QT syndrome (LQTS)." (PMID 26956495, 2016). "Another carried the M54T (rs74315447) in KCNE2, which was reported to alter the transmembrane domain of MiRP1 that reduces potassium currents leading to long QT syndrome and ventricular fibrillation." (PMID 25333069, 2014). "In women with Turner syndrome and a bQTc >432 ms, 7 had mutations in major Long QT syndrome genes (SCN5A and KCNH2) and one in a minor Long QT syndrome gene (KCNE2)." (PMID 23936059, 2013). "Long QT syndrome is caused by mutations in genes encoding cardiac ion channels (such as KVLQT1, HERG, KCNE1, and KCNE2) leading to prolonged cardiac action potential by either increasing depolarization or decreasing repolarization current and so causing syncope, seizures or sudden death." (PMID 23095120, 2012).
cardiac arrhythmia (9 papers, 2007 to 2026). Any disturbances of the normal rhythmic beating of the heart or MYOCARDIAL CONTRACTION. "Kcne2 encodes an ion transmembrane transport and voltage-gated potassium channel protein involved in cardiac arrhythmia." (PMID 36653537, 2023). "KCNE2 encodes the minK-related peptide (MiRP1), which has been linked to hereditary arrhythmias and pro-arrhythmic drug sensitivity." (PMID 17895974, 2007). "Therefore, our data indicates that disease-linked mutations in KCNE2 can alter the stoichiometry and function of Ih complexes in a manner consistent with an increase in susceptibility to cardiac arrhythmias and neuronal disorders such as epilepsy." (PMID 31235733, 2019). "KCNE2 is a functionally versatile, ubiquitously expressed potassium channel β subunit associated with CAD and cardiac arrhythmia susceptibility in humans and mice." (PMID 33464998, 2021). "We validated and optimized the NGS platform with a subset of 46 patients by comparison with Sanger sequencing of coding exons of major arrhythmia risk-genes (KCNQ1, KCNH2, SCN5A, KCNE1, KCNE2, RYR2)." (PMID 31337358, 2019). "By biochemically and pharmacologically dissecting the mechanisms involved, we identify the signaling proteins required for successful prevention by RIPC of Kcne2‐dependent ischemia‐provoked arrhythmias." (PMID 30737904, 2019). "Only three out of 12 RIPC‐liver‐treated and five out of 12 RIPC‐limb‐treated Kcne2‐/‐ mice exhibited arrhythmia (P < 0.001 vs. Kcne2‐/‐ control mice), while the remainder remained in sinus rhythm." (PMID 30737904, 2019). "Thus, all Kcne2‐/‐ mice (15 out of 15, P = 0.0006 vs. Kcne2+/+ mice) developed arrhythmias throughout reperfusion including ventricular tachycardia (VT), atrioventricular block (AVB), polymorphic ventricular tachycardia (PVT), or sustained ventricular tachycardia (SVT) exceeding 10 sec duration." (PMID 30737904, 2019).
diabetes (8 papers, 2008 to 2024). "Second, among 61 previously identified CAD variants in the general population, two—SORT1 and KCNE2—were significantly associated with CAD among individuals with diabetes." (PMID 30003307, 2018). "Deletion of the Kcne2 gene in mice can both provide the electric substrate for arrhythmogenesis by directly disrupting ventricular myocyte repolarization, and can also provide an ischemic substrate by causing atherosclerosis, diabetes, fatty liver and structural heart disease." (PMID 29844497, 2018). "The expression patterns of Kcne2, Nppa, and Dcps provide examples of how restoration of insulin and euglycemia can normalize diabetes-induced gene expression alterations that have occurred before initiation of therapy to non-diabetic levels." (PMID 21575160, 2011). "All 7 confirmed neuronal function-related genes (DCAMKL1, GAT3, GRIN2A, KCNE2, PCGF1, PEPT2, ZNF219) revealed reproducible decreases at 3 months of STZ-induced diabetes." (PMID 18554398, 2008). "Genes such as KCNE2, DLL1, ACVR1C, RGS3, MLXIPL (MLX interacting protein like), PAG1, SLC2A10 and GRB14 play important role in type 2 diabetes mellitus progression." (PMID 33902539, 2021). "In addition, a lack of KCNE2 can lead to dyslipidemia, diabetes and anemia, which in turn can contribute to hyperkalemia and prolongation of the QTC interval of the action potential." (PMID 39272981, 2024).
atherosclerosis (6 papers, 2016 to 2025). A disease characterized by the build-up of fatty material and calcium deposition in the arterial wall resulting in partial or complete occlusion of the arterial lumen. "Demonstrated by mouse knockout models, causal links between KCNE2 and atherosclerosis have been suggested to be due to raising serum LDL and impairing glucose tolerance." (PMID 40182431, 2025). "Other groups found that specific variations or single nucleotide polymorphisms (SNPs) within or near the KCNE2 gene were associated with a higher susceptibility to atherosclerosis, coronary artery disease (CAD) and early heart attack." (PMID 39272981, 2024). "A deficiency of KCNE2 contributes to the development of atherosclerosis and diet-related sudden death by increasing plaque build-up and the formation of premature ventricular complexes, ultimately leading to sudden cardiac death." (PMID 39272981, 2024). "We recently established causality by finding that Kcne2 deletion in mice predisposes to atherosclerosis." (PMID 33464998, 2021). "The findings uncover a novel genetic basis for NAFLD and an unexpected potential factor in human KCNE2-associated cardiovascular pathologies, including atherosclerosis." (PMID 26984260, 2016). "In addition, KCNE2 deficiency in mice promotes the development of atherosclerosis, as well as high-fat diet-dependent ventricular arrhythmia and sudden death." (PMID 39272981, 2024). "The Kcne2–/– mouse data supported the association between CAD and KCNE2 observed in human studies, and are notable because mouse atherosclerosis models are rare and not previously associated with ion channel subunits." (PMID 33464998, 2021).
atrial fibrillation (5 papers, 2011 to 2024). A disorder characterized by an electrocardiographic finding of a supraventricular arrhythmia characterized by the replacement of consistent P waves by rapid oscillations or fibrillatory waves that vary in size, shape and timing and are accompanied by an irregular ventricular response. "Additionally, R27C, M23L and I57T mutations of KCNE2 are associated with familial and early-onset atrial fibrillation." (PMID 39272981, 2024). "Some atrial fibrillation (AF)-associated KCNQ1 and KCNE2 human gene variants augment KCNQ1-KCNE2 currents (which are typically much smaller in terms of outward current even than KCNQ1 alone) and would therefore be predicted to shorten the atrial action potential, thought to predispose to AF." (PMID 24478792, 2014).
channelopathies (4 papers, 2019 to 2025). "Regarding the etiology of channelopathies such as the Congenital Long QT Syndromes itself, 75% of LQTS cases are linked to mutations in genes encoding for voltage-gated potassium channel subunits (KCNQ1, KCNH2, KCNE1, KCNE2), or for voltage-gated sodium channel SCN5A." (PMID 36421220, 2022).
hepatocellular carcinoma (4 papers, 2019 to 2024). A malignant tumor that arises from hepatocytes. "In addition, the results indicate that decreased KCNE2 expression is associated with reduced overall survival in individuals with hepatocellular carcinoma (HCC)." (PMID 39272981, 2024).
iron-deficient anemia (4 papers, 2014 to 2024). "Here we report that Kcne2-deficient mice, in addition to the previously reported phenotypes, also present with iron-deficient anemia." (PMID 25127743, 2014). "In this study, we have generated a targeted gene trap for Kcne2 and identified that mutant male animals suffer from iron-deficient anemia." (PMID 25127743, 2014). "KCNE2 deficiency causes iron deficiency anemia, which can lead to dyslipidemia and NAFLD." (PMID 39272981, 2024). "In addition, Kcne2-deficient mice have been reported to have gastric hyperplasia and neoplasia, achlorhydria 3, 6, anemia, and hypothyroidism." (PMID 25127743, 2014). "Because the Kcne2-linked achlorhydria impairs iron uptake and causes iron deficiency anemia, a potential cause of abnormalities in hepatic lipid metabolism, here we investigated Kcne2-dependent hepatic lipid content and transcriptome remodeling, and discovered that Kcne2 deletion causes NAFLD." (PMID 26984260, 2016). "Using mouse genetics, histology, liver damage assays and transcriptomics we discovered that iron deficiency arising from KCNE2-dependent achlorhydria is a major factor in early-onset NAFLD in Kcne2─/─ mice, while two other KCNE2-dependent defects did not initiate NAFLD." (PMID 26984260, 2016).
ventricular fibrillation (4 papers, 2011 to 2019). A disorder characterized by an electrocardiographic finding of a rapid grossly irregular ventricular rhythm with marked variability in QRS cycle length, morphology, and amplitude. "Two variants, i.e. p.D85N in KCNE1 and p.T8A in KCNE2 have previously been associated with increased risk for drug-induced ventricular fibrillation." (PMID 21967835, 2011). "We report a 37-year-old woman with an out-of-hospital cardiac arrest caused by ventricular fibrillation due to digenic inheritance of long QT syndrome type 2 (KCNH2 gene) and type 6 (KCNE2 gene)." (PMID 31320904, 2019).